FOXP3 (forkhead box P3)
Diseases named in the same sentence as FOXP3 in open-access papers (continued):
Sharing a sentence is not in itself a finding about the gene and the disease.
melanoma (continued). "Based on its infrequent expression in human melanoma, and its growth inhibitory and pro-apoptotic effect in over-expressing melanoma cells, we conclude that FOXP3 is not likely to be a key tumor suppressor or promoter in melanoma." (PMID 24406338, 2014). "On the other hand, the density of FOXP3+ regulatory T lymphocytes in primary melanomas did not prove of prognostic significance." (PMID 23418928, 2013). "In pancreatic cancer and melanoma, FOXP3 expression was restricted to tumor cells and the normal pancreatic ducts or melanocytes were devoid of FOXP3 expression." (PMID 23341929, 2013). "In this retrospective study we determined the density of several immune cell types: OX40+ activated T lymphocytes, FOXP3+ regulatory T cells, DC-LAMP+ mature dendritic cells and CD123+ plasmacytoid DCs in sentinel lymph nodes of patients with malignant melanoma." (PMID 23418928, 2013). "On the other hand, FOXP3+ cell density in metastatic SLNs, but not in tumor-negative ones or in primary melanomas, was found predictive of the outcome of the disease." (PMID 23418928, 2013). "On the other hand, FOXP3+ cell density in SLNs, but not in the primary tumor, was found predictive of disease outcome in melanoma patients." (PMID 23418928, 2013). "In the present study, the levels of Foxp3, CD25 and interleukin (IL)-2 expression were investigated in the B16F10 cancer cell line in vitro and the expression levels of these factors were correlated with tumor growth in a murine model of melanoma." (PMID 24179494, 2013). "STAT3 has been shown to be a key transcriptional regulator of FoxP3 in Tregs, and Treg infiltration has been shown in melanoma patients to be a negative prognosticator and a predictor of local recurrence." (PMID 22488042, 2012). "Implantation of the B16 melanoma in wild-type mice resulted in the enrichment of CD4 Foxp3 Treg in TIL and spleen; this tumor did not induce an enrichment of either CD4 or CD8 Foxp3 in these two transgenic mouse strains." (PMID 22112546, 2011). "In conclusion, phenotypic and functional analyzes strongly suggest that CD4+Foxp3GFP+ T cells that develop in melanoma tumors represent genuine Treg cells and not cells that transiently upregulate Foxp3 without acquiring suppressor function." (PMID 21049016, 2010). "Conversely, significantly elevated FOXP3+ T reg densities were found in responders compared to non-responders in melanoma by IMC analysis of TME which could mediate tumor rejection after the ICIs57." (PMID 38898200, 2024). "Meanwhile, GL incubation effectively reduced the expression of Treg specific markers (Forkhead Box P3, glucocorticoid-induced TNFR-related protein and cytotoxic T lymphocyte antigen 4), phospho-STAT3, COX-2 and prostaglandin E2 in melanoma cells, finally limiting the progression of melanoma." (PMID 37649893, 2023). "Furthermore, we show that melanoma secretome induces downregulation of CTLA4 through miR-155 expression in Treg cells without decreasing their FOXP3 expression." (PMID 37197667, 2023). "Furthermore, according to our results, PD-L1+ stromal immune and melanoma cells associated positively with IDO+ stromal immune and tumor cells, but not with TAMs or FoxP3 Tregs." (PMID 36551965, 2022). "In the co-culture assays, we evaluated the potential of melanoma patient B cells to mediate modulation of autologous CD4+ T-helper cell phenotype and functions, including the modulation of T cell proliferation, TNF-α, IFN-γ, and FOXP3 expression and induction of FOXP3+ Tregs." (PMID 35909944, 2022). "Fresh PBMC and tumor associated cells were isolated from a separate cohort of canine melanoma patients (P21-31) and tested by an abbreviated flow cytometry panel that included interrogation for CD3+ T cell subsets (CD4+, CD4-CD8-, and CD8+), FoxP3 and granzyme B." (PMID 34926643, 2021).
melanoma (continued). "FoxP3+ frequencies within the CD4+ T cell subset in fresh PBMC for this patient cohort (n = 11) were higher compared to fresh PBMC isolated from healthy controls (n = 10; C14-23) (p = 0.043), although the difference was modest as shown for other melanoma patients." (PMID 34926643, 2021). "Another study in BRAF V600E mouse melanoma transplants and in de novo melanomas demonstrated that BRAF inhibitor downregulated tumor expression of chemokine (C-C motif) ligand 2 (CCL2), and resulted in a robust increase in CD8+ T/FoxP3+CD4+ T cell ratio and natural killer (NK) cells." (PMID 29156850, 2017). "Analysis of biopsies from melanoma lesions treated by intratumoral T-VEC injection induced both local and systemic T lymphocyte responses, as well as decreased CD4+FoxP3+ regulatory T cells (Tregs) and CD8+FoxP3+ suppressor T cells (Ts), both of which are inversely correlated with patient survival." (PMID 28536385, 2016). "Furthermore, inflammatory TH2-biased conditions such as IL-10, IL-4, VEGF and FoxP3+ Tregs that support class switching to IgG4 rather than IgE, and elevated IgG4 levels have been reported in different tumors including melanoma." (PMID 27471625, 2016). "However, this analysis did not quantify the percentage of melanomas which express FOXP3, or the percentage of FOXP3 positive cells within a tumor." (PMID 24406338, 2014). "From the present data, it may be suggested that Foxp3 participates in tumor growth and the modulation of the IL-2, IFN-γ and TNF-α cytokines and CD25, and that it may play a role in the immunosuppression of melanomas, possibly via this pathway." (PMID 24179494, 2013). "Based on more recently described clinical findings of a Foxp3 expression in cancer cells of tumors like lung, hepatocellular, and urinary bladder cancer as well as melanoma we suggested that elevated Foxp3 expression levels were not necessarily associated to Treg alone but also to cancer cells." (PMID 23382847, 2013). "FOXP3 is also expressed in human melanoma cells but not in normal melanocytes." (PMID 23888189, 2012). "However, incomplete Freund’s adjuvant (IFA), in a clinical trial of a melanoma vaccine, demonstrated that 1–3 injections induce accumulation of mature dendritic cells, while 4–6 injections induce FoxP3+ T cells and eosinophils and negative immune regulatory processes in the site." (PMID 37514985, 2023). "The expression pattern of forkhead box protein P3 (FOXP3) in tumor-infiltrating lymphocytes of primary cutaneous melanoma (PCM) suggests that FOXP3-expressing lymphocytes may suppress the local anti-PCM immune response in the microenvironment, thus favoring melanoma progression." (PMID 34489925, 2021). "In conclusion, we showed that PDT targeting CD25+Foxp3+ tumor-infiltrated Tregs could achieve selective depletion of Tregs within the tumor microenvironment without inducing systemic side effects in a mouse melanoma model." (PMID 28537894, 2017). "According to the same authors, their study clearly demonstrates that FOXP3 expression is not restricted to pancreatic carcinoma cells but seems to characterize many other tumors not only of epithelial (e.g., lung, breast, and colon) but also of other tissue origins (melanoma, leukemia)." (PMID 24877082, 2014). "Our findings demonstrate for the first time the negative prognostic value of low FOXP3 TIL count and confirm a negative prognostic value of negative tumour PD-L1 expression in melanoma lymph node metastases." (PMID 39883679, 2025). "In contrast, CD8+ T cell phenotypes in CTLA4res melanoma were indistinguishable from ICB naïve melanoma; however, instead, an increase of FOXP3+ T cells was observed." (PMID 38594286, 2024). "Nevertheless, melanoma and lung cancer surely share common characteristics proven in previous studies, such as high average TMB and FoxP3 expression in tumor cells or TILs representing negative prognostic factors." (PMID 36980787, 2023).
melanoma (continued). "We assessed TIL profile in 57 cases of vertical growth phase melanomas with either brisk or nonbrisk TIL, using immunohistochemical staining for CD3, CD8, and coexpression of CD8 and FoxP3 double stain." (PMID 25954764, 2015). "The CD8+:FOXP3+ T cell ratio in ICI-non-resistant AYA melanomas was similar to the adult groups, while the resistant AYA group showed a trend of lower CD8+:FOXP3+ cell ratio compared to adult non-resistant melanomas (P = 0.085)." (PMID 38589406, 2024). "Some MAGE-specific Tregs that were isolated from melanoma patients vaccinated with MAGE were CD4+CD25+ and demethylated FOXP3, whereas other CD4+ clones lacking CD25 could also suppress Teff cells, despite FOXP3 being methylated." (PMID 38891073, 2024). "FoxP3 mRNA-transfected DC vaccines reduced intratumoral, but not systemic, FoxP3+ Treg and bolstered TRP2-specific CTL responses following co-vaccination with TRP2-pulsed DCs in a murine melanoma model." (PMID 26082780, 2015). "Furthermore, we show that FoxP3+ Tregs appear to contribute to the immunosuppressive TME in CM, but their role may not be that critical to melanoma progression." (PMID 34051744, 2021). "Moreover, by combining two negative biomarkers, FoxP3 (Tregs) and CD68 (TAMs), we can select an even more specific group of patients who benefited from treatment with PD-1 inhibitors the most, and in the melanoma subgroup, we confirmed its predictive value but not prognostic." (PMID 36980787, 2023).
asthma (193 papers, 2008 to 2026). "This study is the first to so clearly show that FOXP3 levels fluctuate significantly depending on a variety of environmental factors associated with asthma." (PMID 36981683, 2023). "Exposition to antibiotics up to the age of 2 years was associated with risk level seven times higher (p = 0.019), and with FOXP3 higher by one, a 6% lower risk of asthma was observed (p = 0.001)." (PMID 36981683, 2023). "Significant importance for asthma risk was identified for the prevalence of other allergic diseases, exposition on antibiotics up to 2 years, and FOXP3." (PMID 36981683, 2023). "The results of our research showed that environmental factors can influence the level of FOXP3, which in turn leads to an increased risk of asthma." (PMID 36981683, 2023). "Our study analyzed various environmental factors in relation to the risk of developing asthma as well as the level of FOXP3 in relation to selected factors and examined how it changes depending on their occurrence." (PMID 36981683, 2023). "Breastfeeding, the coexistence of other allergic diseases, and the frequency of housekeeping all affect FOXP3 levels, which are negatively correlated with the risk of asthma." (PMID 36981683, 2023). "Breastfeeding, the coexistence of other allergic diseases, and the frequency of housekeeping affect FOXP3 levels, which are negatively correlated with the risk of asthma." (PMID 36981683, 2023). "Paradoxically, Foxp3+ Treg cells are implicated in immunological homeostasis, suppressing allergic responses, and limiting inflammation in asthma." (PMID 35664352, 2022). "Treg stability and suppressive function are maintained by Foxp3 expression, and mutations in Foxp3 are linked to inflammatory diseases, including Crohn’s disease, obesity, and asthma." (PMID 35025767, 2022). "In contrast, our findings show that the Imuno TF upregulated the Foxp3 expression associated to increase of IL-10 secretion in lung of asthma animals, indicating that Imuno TF also upregulates Treg cells response." (PMID 36685604, 2022). "Another important immune cell type that has been implicated in the pathology of asthma are regulatory T cells (Tregs) that express the transcription factor Foxp3." (PMID 35386975, 2021). "A significant increase in DNA methylation and an associated decrease in Foxp3 expression in Treg cells were detected in 256 AR or juvenile asthma patients." (PMID 34239942, 2021). "These prior studies found that differentially methylated regions (DMRs) in the FOXP3 promoter and IL10 genes were different in children with asthma, and in the case of FOXP3 methylation, also associated with exposure to ambient air pollution." (PMID 34299914, 2021). "Resveratrol, a natural phenol compound commonly found in peanuts, wine, berries, and red grapes, suppresses the asthma-associated immune response mediated by the upregulation of FOXP3 through downregulation of miR-34a." (PMID 34566492, 2021). "Epigenetic modifications of Treg cells (i.e., cytosine methylation at the promoter region of the transcription factor, Forkhead Box P3) have been found to be closely associated with allergic diseases, including allergic rhinitis, asthma, and food allergies." (PMID 34239942, 2021). "Epigenetic modifications, such as the transcriptional silencing of FOXP3, via hypermethylation of CpG islands in the promoter and intronic regions, have been associated with poor outcomes in children with asthma." (PMID 32210181, 2020). "The concentration of Treg cells, as well as FoxP3 expression and IL-10 production are deficient in asthma thereby contributing to airway inflammation and disease activity." (PMID 30967873, 2019). "To assess the association between CD15+ Treg cells and asthma, we compared the proportion of sialyl LeX positive FOXP3+ Treg cells among CD4+ T cells between intermittent-to-mild (n = 20) and moderate-to-severe (n = 11) asthma and healthy controls (n = 19)." (PMID 31222115, 2019).
asthma (continued). "We found that asthma was significantly associated with methylation at four of the six CpG sites in the promoter region of Foxp3 (p < 0.05)." (PMID 29317916, 2018). "In summary, our study showed that oral administration of resveratrol suppressed the asthma-associated immune response and its action was mediated by upregulation of FOXP3 induced by miR-34a down-regulation." (PMID 30619345, 2018). "We found methylation at the upstream promoter region of Foxp3 to be associated with both asthma status and exposure to AAPs." (PMID 29317916, 2018). "Asthma was significantly associated with higher differentially methylated regions (DMRs) of the Foxp3 promoter region (p = 0.030) and the IL10 intronic region (p = 0.026)." (PMID 29317916, 2018). "This is the first study to show that the protective effects of pitavastatin against asthma are associated with CD4+ CD25+ Foxp3+ T cells." (PMID 28729731, 2017). "Increased exposure to ambient air pollution was also associated with hypermethylation of FOXP3, which coincided with impaired Treg function and increased asthma morbidity." (PMID 27777592, 2016). "GWAS are the most powerful approach to identify the genetic risk for asthma, but candidate gene studies are the most common, and the results of these studies on FOXP3 are discussed here." (PMID 27965764, 2015). "This said, epigenetic studies using pyrosequencing have also associated other loci on the FOXP3 gene, such as its promoter region, with various immune-related disease states such as asthma, food allergy, auto-immunity and cancer." (PMID 26500760, 2015). "Taken together, these results all show that polymorphism in FOXP3 gene is associated with some allergic disease, but its contribution to asthma has been poorly studied." (PMID 27965764, 2015). "Polymorphisms in the FOXP3 gene have been associated with some allergic diseases but the contribution of these polymorphisms to asthma development has been poorly studied." (PMID 27965764, 2015). "The main approach to control allergy and asthma is corticosteroid therapy, either ingested or inhaled, both of which are associated with enhanced Foxp3+ expression and an increased suppressor function." (PMID 27965764, 2015). "Further investigation will be important to clarify the role of FOXP3 polymorphisms and epigenetics mechanisms on the risk of asthma and other allergic diseases." (PMID 27965764, 2015). "Ambient air pollution is associated with hypermethylation of FOXP3 in regulatory T cells, impairing their suppressive function and increasing asthma morbidity." (PMID 24039973, 2013). "Moreover, the oral administration of resveratrol suppresses the asthma-associated immune response mediated by the upregulation of FOXP3 and downregulation of miR-34a." (PMID 39263346, 2024). "We hypothesized whether environmental factors can affect FOXP3 levels and thus have an impact on the risk of developing asthma." (PMID 36981683, 2023). "Studies in animals suggest the Foxp3+ pTregs and IL-10-producing Tr1 cells may contribute to the differences of asthma susceptibility associated with different genetic background." (PMID 35757774, 2022). "In another study in mice with induced allergic asthma, resveratrol downregulated the expression of miR-34a, with consequent overexpression of FOXP3, a critically important transcription factor for the development and function of asthma-implicated regulatory T-cells (Tregs)." (PMID 35912113, 2022). "Foxp3 and IL-13 gene acetylation is associated with childhood asthma." (PMID 34566492, 2021). "Diesel exhaust particle exposure was associated with alterations in Alu and LINE-1 elements and the CpG site within miR-21, and increased FOXP3 was significantly associated with increased diesel exhaust particle exposure, which was associated with increased risk of asthma development in children." (PMID 32047643, 2019).